PMP22 (peripheral myelin protein 22)
Diseases named in the same sentence as PMP22 in open-access papers (continued):
Sharing a sentence is not in itself a finding about the gene and the disease.
neuropathy (continued). "This PMP22 duplication test has the highest yield in patients with a definite neuropathy subtype as defined by electrodiagnostic data and who are also evaluated by specialized neuropathy clinics." (PMID 36313509, 2022). "Eight unrelated neuropathy patients had heterozygous PMP22 duplication." (PMID 35938991, 2022). "Moreover, most PMP22 missense mutations are transmitted in an autosomal dominant pattern, except for R157W and T118M, which have been detected in the homozygous state, indicating the genetic and clinical diversity of PMP22-related neuropathy." (PMID 32719652, 2020). "To date, 10 point mutations in the PMP22 genes result in hearing loss associated with the neuropathy, not including the R157W and W39C mutations identified in our study." (PMID 32719652, 2020). "Duplication of the human peripheral myelin protein 22 (PMP22)/growth arrest-specific gene 3 (gas-3), is responsible for Charcot–Marie–Tooth type 1 A (CMT1A) neuropathy, while haploinsufficiency is linked with hereditary neuropathy with liability to pressure palsy (HNPP)." (PMID 31455873, 2019). "The Pmp22−/− mouse model displays a more severe neuropathy as compared to Pmp22 haploinsufficiency." (PMID 27799291, 2016). "The main result of this study is that among 44 patients that had been previously screened negative for point mutations and small indels in 51 peripheral neuropathy genes only one CNV, a PMP22 duplication, was detected in known neuropathy genes by whole-genome CNV analysis." (PMID 25648254, 2015). "PMP22 related neuropathies are the most prevalent amongst the inherited neuropathies." (PMID 24646194, 2014). "While the three mentioned protein homoeostatic mechanisms have been associated with pathobiology of PMP22-linked neuropathies, their potential contribution to disease progression has not been examined in detail." (PMID 24175617, 2013). "CMT1A patients have the PMP22 duplication and, although subacute, acute, and chronic inflammatory demyelinating polyneuropathy forms have been described, the patients display typical phenotype of neuropathy, with reduced nerve conduction velocity and demyelination." (PMID 29036910, 2017). "A protective role for chaperones in neuropathies is supported by studies where exogenous induction of the heat-shock response either by diet restriction or pharmacologic modulation prevents the aggregation of PMP22 while promoting the myelination capacity of the Schwann cells." (PMID 24175617, 2013). "According to larger studies following comparable protocols, we can genetically identify the four most frequent genes (PMP22, GJB1/Cx32, MPZ/P0, MFN2) in 40–60% of patients in whom an inherited neuropathy is suspected." (PMID 34438578, 2021). "When used in the Tr-J mouse model, a PMP22 mutant mouse model to study CMT1A, curcumin reduced neuropathy in a dose-dependent manner." (PMID 31336816, 2019). "We also report here that Niaspan is effective in reducing the number of tomacula in the Pmp22+/− mouse, a model of the HNPP (hereditary neuropathy with liability to pressure palsies) neuropathy." (PMID 27799291, 2016). "Animal models that overexpress PMP22 recapitulate the CMT1A phenotype, and the neuropathy can be clinically, electrophysiologically, and neuropathologically corrected by abrogation of the overexpression using epigenetic manipulation of PMP22 gene expression." (PMID 16444292, 2005). "Because numerous studies have revealed that the dosage of PMP22 may determine the type and severity of the related neuropathy, such as CMT or HNPP, treatment strategies should target the direct pathways affected by the PMP22 gene dosage." (PMID 40940747, 2025). "Of note, the diagnostic yield in the neuropathy subgroup also needs to be interpreted with caution, as testing for PMP22 (CMT1A) duplications is usually performed prior to NGS in our department, and the combined yield in an unselected neuropathy cohort would therefore most probably be higher." (PMID 38127101, 2024).
neuropathy (continued). "Severity of CMT1A is dependent on PMP22 copy number, as patients with four rather than three copies have a more severe neuropathy." (PMID 31455873, 2019). "CNVs were detected affecting genes where deletions or duplications are established as a common mechanism, like PRKN (in Parkinson’s disease), DMD (in Duchenne muscular dystrophy) and PMP22 (in neuropathies), but also genes in which no intragenic CNVs have been reported to date." (PMID 36781956, 2023). "However, it still accounts for 7.5% of molecularly unassigned demyelinating CMT in the absence of PMP22 duplication, GJB1 mutations or MPZ mutations, as well as 1.9% of HNPP-like neuropathy of unknown genetic causes in Taiwan." (PMID 29127354, 2017). "However, 54% of our Norwegian CMT families from the general population remained without a genetic diagnosis after exclusion of the PMP22 duplication and the NGS sequencing of 33 CMT genes and 19 other neuropathy genes." (PMID 25648254, 2015).
hereditary neuropathy with liability to pressure palsies (42 papers, 2005 to 2026). "Hereditary neuropathy with liability to pressure palsies (HNPP) is a genetic disorder linked to deletions in the PMP22 gene, which contrast with PMP22 duplications that cause Charcot–Marie–Tooth disease type 1A (CMT1A)." (PMID 40309874, 2025). "Haplo-insufficiency of PMP22 causes hereditary neuropathy with liability to pressure palsies (HNPP)." (PMID 38383802, 2024). "Haplo-insufficiency of the gene encoding the myelin protein PMP22 leads to focal myelin overgrowth in the peripheral nervous system and hereditary neuropathy with liability to pressure palsies (HNPP)." (PMID 38383802, 2024). "Hereditary neuropathy with liability to pressure palsies (HNPP) is a recurrent, episodic demyelinating neuropathy, most commonly caused by a 17p11.2 chromosomal deletion encompassing the PMP22 gene." (PMID 35658923, 2022). "Deletion events encompassing PMP22 are associated with autosomal dominant hereditary neuropathy with liability to pressure palsies (HNPP, MIM# 162500) leading to numbness, tingling and muscle weakness in the limbs." (PMID 36414972, 2022). "Hereditary neuropathy with liability to pressure palsies (HNPP) is caused by heterozygous deletion of peripheral myelin protein‐22 (PMP22) gene." (PMID 32856791, 2020). "Hereditary neuropathy with liability to pressure palsies (HNPP) is caused by heterozygous deletion of the peripheral myelin protein 22 (PMP22) gene." (PMID 31872979, 2020). "Hereditary Neuropathy with Liability to Pressure Palsies (HNPP) is caused by a heterozygous deletion of peripheral myelin protein‐22 (PMP22) gene resulting in focal sensorimotor deficits." (PMID 32856791, 2020). "In contrast to PMP22 overexpression in CMT1A disease, a heterozygous deletion of the PMP22 gene causes hereditary neuropathy with liability to pressure palsies (HNPP)." (PMID 30050403, 2018). "Deletion of one of two copies of the PMP22 gene causes hereditary neuropathy with liability to pressure palsies (HNPP)." (PMID 27583434, 2016). "The second group is caused by a PMP22 deletion, leading to Hereditary Neuropathy with liability to Pressure Palsies (HNPP)." (PMID 24646194, 2014). "Charcot-Marie-Tooth disease type 1A (CMT1A) and hereditary neuropathy with liability to pressure palsies (HNPP) are dysmyelinating peripheral neuropathies that result from an altered dosage of PMP22, which encodes peripheral myelin protein." (PMID 16444292, 2005). "Another clinical condition mimicking some of the symptoms of the patients presented here is hereditary neuropathy with liability to pressure palsies (HNPP), an autosomal dominant inherited disorder usually caused by under-production of PMP-22 due to a partial deletion on chromosome 17." (PMID 35296359, 2022). "The deletion of this region and point mutations and small deletions in the PMP22 gene are less common and may cause hereditary neuropathy with liability to pressure palsies (HNPP), Dejerine-Sottas neuropathies (DSS) and CMT1E." (PMID 32719652, 2020). "Duplications and deletions of the gene encoding peripheral myelin protein 22 (PMP22) cause the most common forms of Charcot-Marie-Tooth (CMT) disease: type 1A (CMT1A) and hereditary neuropathy with liability to pressure palsies (HNPP), respectively." (PMID 42320627, 2026). "Charcot–Marie–Tooth Disease Type 1A (CMT1A) and Hereditary Neuropathy with Liability to Pressure Palsies (HNPP) are the most common inherited peripheral neuropathies and arise from copy number variation of the Peripheral Myelin Protein 22 (PMP22) gene." (PMID 41400104, 2026). "The genetic counterpart of CMT1A is the hereditary neuropathy with liability to pressure palsies (HNPP), in which patients present lower PMP22 copy number (one single allele) and episodic motor and/or sensory deficits." (PMID 34573256, 2021).
hereditary neuropathy with liability to pressure palsies (continued). "The deletion encompasses the PMP22 gene, whose haploinsufficiency is responsible for hereditary neuropathy with liability to pressure palsies (HNPP) (MIM 162500)." (PMID 33466780, 2021). "Hereditary neuropathy with liability to pressure palsies (HNPP) is an autosomal dominant disorder mainly due to a deletion of chromosome 17p11.2 including PMP22 (PMP22 Del HNPP)." (PMID 29544507, 2018). "In the present study, we have demonstrated the disruption of myelin junctions in a mouse model (Pmp22+/-) of hereditary neuropathy with liability to pressure palsies (HNPP) with heterozygous deletion of Pmp22 gene." (PMID 27583434, 2016). "In contrast, heterozygous deletion of PMP22 (approximately 0.5-fold reduction in expression) leads to another demyelinating neuropathy, Hereditary Neuropathy with Liability to Pressure Palsies (HNPP)." (PMID 41234933, 2025). "Hereditary neuropathy with liability to pressure palsies (HNPP), which is a peripheral myelin protein 22 (PMP22) gene‐related genetic disorder similar to CMT type 1A, is characterized by repetitive painless mononeuropathies and plexopathies triggered by minor trauma of the peripheral nerves." (PMID 28948078, 2017). "This knockout model is especially relevant because the peripheral myelin protein 22 (PMP22) is closely connected with several hereditary human PNS neuropathies, including Charcot-Marie-Tooth1A (CMT1A) and hereditary neuropathy with liability to pressure palsies (HNPP)." (PMID 28912683, 2017).
Charcot-Marie-Tooth disease (38 papers, 2009 to 2026). An inherited degenerative disorder involving the peripheral nerves. "For example, patients with Charcot-Marie-Tooth disease due to duplication of the PMP22 gene are at higher risk of permanent neurological complications after treatment with certain antineoplastic agents." (PMID 38740897, 2024). "Pmp22 mutations were pathognomonic for the main peripheral hereditary neuropathies Charcot-Marie-Tooth disease (CMT)." (PMID 35327648, 2022). "Mutations or deletions in different parts of the PMP22 gene can lead to hereditary peripheral nervous system diseases, including Charcot Marie Tooth disease (CMT), and hereditary neuropathy with liability to pressure palsies (HNPP)." (PMID 36217151, 2022). "These numbers suggest that RFC1 is among the three most common genetic causes of Charcot-Marie-Tooth disease in Finland together with PMP22 duplication and p.His123Arg in GDAP1." (PMID 34600502, 2021). "The most common type of Charcot-Marie-Tooth disease is caused by a duplication of PMP22 leading to dysmyelination, axonal loss and progressive muscle weakness (CMT1A)." (PMID 30650121, 2019). "Examples include the HERG potassium channel and cardiac arrhythmia, the human peripheral membrane myelin protein 22 (PMP22) and Charcot-Marie Tooth disease, and a subset of mutations in the cystic fibrosis transmembrane conductance regulator (CFTR) protein." (PMID 31518351, 2019). "In peripheral nervous system, mutation in peripheral myelin protein 22 (PMP22) is linked to Charcot-Marie-Tooth disease, a sensorineural peripheral polyneuropathy." (PMID 29515361, 2018). "Point mutations in the peripheral myelin protein 22 (PMP22) gene have been identified to cause demyelinating Charcot-Marie-Tooth disease (CMT) and hereditary neuropathy with liability to pressure palsy (HNPP)." (PMID 29127354, 2017). "The most common genetic cause of the inherited peripheral neuropathy Charcot-Marie-Tooth disease is the PMP22 duplication; otherwise, CNVs have been considered rare." (PMID 25648254, 2015). "We describe a unique patient who had been diagnosed with inflammatory demyelinating polyneuropathy (CIDP) for 13 years with frequent clear responses to immunotherapies and was finally diagnosed with Charcot-Marie-Tooth disease (CMT) with a rare point mutation in PMP22 (c.320G > A, p.G107D)." (PMID 40126701, 2025). "Interestingly, this patient has also a duplication of the PMP22 gene, associated with Charcot-Marie-Tooth disease, although he remains asymptomatic." (PMID 38956727, 2024). "The peripheral myelin protein-22 (PMP22) duplication is the most common cause of Charcot-Marie-Tooth disease (CMT)." (PMID 40126701, 2025). "PMP22 mutations were pathognomonic for human hereditary peripheral neuropathies, including the Charcot-Marie-Tooth disease (CMT)." (PMID 35327648, 2022). "The PMP22 gene encodes a 22 kDa glycoprotein member of an extended family of tetraspan membrane proteins that play important roles in myelin membrane formation and, when mutated, are responsible for a set of inherited peripheral neuropathies, including Charcot-Marie-Tooth disease." (PMID 26672768, 2016). "It is useful to note that penetrance for ID in the 17p12 [PMP22] deletion for Hereditary Neuropathy with Liability to Pressure Palsies and the reciprocal duplication for Charcot Marie Tooth Disease is 0%." (PMID 41094176, 2026). "Charcot-Marie-Tooth disease (CMT) is a genetically heterogeneous hereditary neuropathy, and CMT1A is the most common form; it is caused by a duplication of the peripheral myelin protein 22 (PMP22) gene." (PMID 34996390, 2022). "A previous study reported that Charcot-Marie-Tooth disease was related to the retention of a peripheral myelin protein 22 (PMP22) mutant regulated by RER1 and calnexin." (PMID 30630537, 2019).
Charcot-Marie-Tooth disease (continued). "Mutation in the peripheral myelin protein 22 (PMP22) and its accumulation in endoplasmic reticulum gives rise to Charcot-Marie-Tooth (CMT) disease, a common peripheral nervous system disorder." (PMID 28890687, 2017). "In addition, the PMP22 (peripheral myelin protein 22) gene on chromosome 17, previously reported to be associated with Charcot Marie Tooth (CMT) disease or hereditary neuropathy with pressure palsies (HNPP), may also play an important role in susceptibility to TB." (PMID 27623071, 2016). "Based on the method of CNV detection above, we identified heterozygous duplications of CDS1-4 in the PMP22 gene in patient P57 who were diagnosed with Charcot-Marie-Tooth (CMT) disease." (PMID 26274329, 2015). "Both hereditary sensorimotor neuropathy due to PMP22 duplication (CMT1A) and facioscapulohumeral muscular dystrophy (FSHD) due to a shortened fragment of the D4Z4 locus (19 kb) were identified in the described patient." (PMID 24041033, 2013). "The only nonsense mutation (chr17:15142830C->G) that is specific to Tianjiao1 is located in the PMP22 gene (peripheral myelin protein 22 [HGNC 9118]) and has been associated with Charcot-Marie-Tooth disease (CMT1A, [MIM 118220])." (PMID 23874230, 2013). "Only eight of the events (all hotspot sites) associated with genomic disorders, including 22q11.2 deletion (TBX1, DiGeorge syndrome), 17p12 duplication (PMP22, Charcot-Marie-Tooth disease), and 15q11.2q13.1 duplication (UBE3A and SNRPN)." (PMID 22102821, 2011). "In previous studies we showed that high concentrations of AA down-regulate the cAMP-dependent expression of PMP22, partially correcting Charcot-Marie Tooth disease phenotype in mouse models." (PMID 19197388, 2009). "Recently, we demonstrated that high concentrations of AA act on PMP22 gene expression and partially correct the Charcot-Marie-Tooth disease phenotype in a mouse model." (PMID 19197388, 2009). "In the case of Charcot-Marie-Tooth disease, models of hiPSCs-derived motor neurons have been established for different forms associated to different genes, such as NELF, MFN2, HSPB1, but also hiPSCs-derived Schwann cells presenting the PMP22 duplication." (PMID 34440148, 2021). "Myocardial involvement in a case like Charcot-Marie-Tooth disease could be due to partial homology of the PMP22 protein with other proteins expressed in the heart, such as EMP or MP20." (PMID 26180644, 2015). "A 25-year-old male with a diagnosis of Charcot Marie Tooth disease (CMT; attributed to the PMP22 gene) presented with distal progressive numbness, weakness, and muscle wasting in the legs beginning when he was 11 years old." (PMID 38344215, 2024). "Charcot-Marie-Tooth disease (CMT) is a hereditary motor sensory neuropathy and Charcot-Marie-Tooth type 1A (CMT1A), a demyelinating form due to duplication of PMP22 gene, represents the most frequent subtype." (PMID 33899151, 2022).